ARPC4 (actin related protein 2/3 complex subunit 4)
Description:
Actin-binding component of the Arp2/3 complex, a multiprotein complex that mediates actin polymerization upon stimulation by nucleation-promoting factor (NPF). The Arp2/3 complex mediates the formation of branched actin networks in the cytoplasm, providing the force for cell motility. In addition to its role in the cytoplasmic cytoskeleton, the Arp2/3 complex also promotes actin polymerization in the nucleus, thereby regulating gene transcription and repair of damaged DNA. The Arp2/3 complex promotes homologous recombination (HR) repair in response to DNA damage by promoting nuclear actin polymerization, leading to drive motility of double-strand breaks (DSBs).
Synonyms: p20-ARC; ARC20; DEVLO
Tractability: Small molecule: a structure with a bound ligand is known. PROTAC: ubiquitination databases record sites on it; its protein half-life has been measured.
Gene: Protein-coding gene on chromosome 3 (9,792,493 to 9,807,107, forward strand). Ensembl gene ENSG00000241553.
Subcellular location: Cytoplasm, cytoskeleton; Cell projection; Nucleus
Pathways (Reactome):
Developmental Biology: EPHB-mediated forward signaling
Disease: FCGR3A-mediated phagocytosis
Immune System: Regulation of actin dynamics for phagocytic cup formation
Signal Transduction: RHO GTPases Activate WASPs and WAVEs
Vesicle-mediated transport: Clathrin-mediated endocytosis
Gene Ontology:
Molecular function: actin filament binding; enzyme binding; protein binding; protein-macromolecule adaptor activity; structural constituent of cytoskeleton
Biological process: Arp2/3 complex-mediated actin nucleation; actin nucleation; actin filament polymerization
Cellular component: Arp2/3 protein complex; extracellular exosome; nucleus; actin cytoskeleton; cytosol; site of double-strand break; cytoskeleton
Genetic constraint (gnomAD): Loss-of-function variants: 3 observed, 21.42 expected, observed/expected ratio (o/e) 0.14, 90% interval 0.063 to 0.36. The upper end of that interval is the gene's LOEUF score, 0.36, which puts it in group 1 of 6, group 1 being the genes least tolerant of losing a copy. Missense variants: 98 observed, 217.77 expected, observed/expected ratio (o/e) 0.45, 90% interval 0.38 to 0.53. Synonymous variants: 80 observed, 76.16 expected, observed/expected ratio (o/e) 1.05, 90% interval 0.88 to 1.26.
Homologues: Orthologues: dog ARPC4 (100% identical), mouse Arpc4 (100% identical), rat Arpc4 (100% identical), chimpanzee ARPC4 (99% identical), guinea pig ARPC4 (99% identical), rabbit ARPC4 (99% identical), zebrafish arpc4l (98% identical), tropical clawed frog arpc4 (98% identical), zebrafish arpc4 (98% identical), Drosophila melanogaster Arpc4 (83% identical), Caenorhabditis elegans arx-6 (77% identical).
Diseases named in the same sentence as ARPC4 in open-access papers:
ARPC4 is named in the same sentence as 23 diseases in open-access papers, as found by Europe PMC text mining. Sharing a sentence is not in itself a finding about the gene and the disease. The quoted sentences say what the papers report.
mastitis (5 papers, 2020 to 2025). Inflammation of breast tissue during lactation or postpartum due to an obstructed duct or infection. "Comparison with indigenous pigs showed genes that were associated with mastitis resistance (ARHGAP39, ARPC4, PHC2, and BCL2L15) and hair follicle development (FOXN1)." (PMID 32457791, 2020). "In summary, CB significantly mitigates inflammatory damage in LPS-induced mastitis models by suppressing inflammatory cytokine production, inhibiting apoptosis, and downregulating ARPC3, ARPC4, and HSP70 expression." (PMID 40243637, 2025). "Future studies should explore these multidimensional interactions to further elucidate the molecular mechanisms by which ARPC3/ARPC4 and HSP70 regulate bovine mastitis progression." (PMID 40305275, 2025). "In our previous research, proteomic analysis unveiled that LTA induces mastitis by modulating ARPC3 and ARPC4, thereby activating the host immune response." (PMID 39199289, 2024). "This research will establish a solid foundation for future studies, elucidating the regulatory roles of key factors ARPC3, ARPC4, and HSP70 in dairy cow mastitis, thereby facilitating the identification of new therapeutic targets for this condition." (PMID 39199289, 2024). "Our results demonstrate that CB significantly alleviates mastitis symptoms by suppressing inflammatory responses, inhibiting apoptosis, and downregulating key molecules including ARPC3, ARPC4, and HSP70, thereby providing a theoretical basis for its potential therapeutic application." (PMID 40243637, 2025).
hepatocellular carcinoma (2 papers, 2021 to 2025). A malignant tumor that arises from hepatocytes. "Thus, the subunit 4 (ARPC4) is associated with reduced survival in patients with hepatocellular carcinoma." (PMID 34442830, 2021).
pancreatic carcinoma (2 papers, 2021 to 2023). "Similarly, significant overexpression of ARPC4 has also been observed in pancreatic carcinoma and gastric carcinoma, indicating a close association between APRC4 expression and tumor migration and invasion." (PMID 34307456, 2021).
psoriasis (2 papers, 2024 to 2025). An autoimmune condition characterized by red, well-delineated plaques with silvery scales that are usually on the extensor surfaces and scalp. "The knockdown of ARPC3 leads to tight junction dysfunction in cells, while the knockdown of ARPC4 causes skin complications similar to psoriasis." (PMID 40305275, 2025). "Indeed, CK14-Cre-driven knockout of ARPC4 leads to a psoriasis-like phenotype and a downregulation of DSG1 and DSC129." (PMID 39271654, 2024).
Salmonella Infections (2 papers, 2019 to 2022). Infections with bacteria of the genus SALMONELLA. "Other genes known to be associated with Salmonella infection were also upregulated, including a variety of chemokines, RELA, ARPC4 and MAPK3." (PMID 35711662, 2022). "The role of the Arp2/3 complex in Salmonella infections has been somewhat conflicting (17, –, 19), but here we demonstrated that mutants with clonal mutations generated in the ACTR3 and ARPC4 genes showed strong resistance to S. Typhimurium infections." (PMID 31594818, 2019).
bladder transitional cell carcinoma (1 paper, 2025). The most common morphologic subtype of urinary bladder carcinoma (over 90% of cases). "Research has shown that knocking down ARPC4 in Human Bladder Transitional Cell Carcinoma (T24 cells) inhibits pseudopod formation, and downregulating ARPC4 suppresses filamentous actin cytoskeleton synthesis." (PMID 40305275, 2025).
Cognitive impairment (1 paper, 2023). Abnormal cognition is characterized by deficits in thinking, reasoning, or remembering. "Therefore, the altered expression of both ARPC4 and STMN1 proteins in the hippocampus of our old samples let us hypothesize and confirm that a cognitive impairment may also occur in bovine during the physiologic aging." (PMID 37965495, 2023).
idiopathic pulmonary fibrosis (1 paper, 2025). Idiopathic pulmonary fibrosis (IPF) is a nonneoplastic pulmonary disease that is characterized by the formation of scar tissue within the lungs in the absence of any known cause. "Using the Idiopathic Pulmonary Fibrosis (IPF) Cell Atlas, we found increased expression of phagocytosis-related genes (FCGR1A, ARPC4, ARPC5) in IPF patients across multiple datasets (available at Rheumatology online)." (PMID 39672802, 2025).
Immunodeficiency (1 paper, 2025). Failure of the immune system to protect the body adequately from infection, due to the absence or insufficiency of some component process or substance. "In this respect, mutations in ARPC1B, ARPC4 and ARPC5, which encode components of the Arp2/3 complex, have been identified as the cause of several genetic disorders, characterised by either immunodeficiency and thrombocytopenia or microcephaly and neurodevelopmental defects." (PMID 40368919, 2025).
Yersinia infection (1 paper, 2022). "Conclusively, the mechanisms of action of ARPC3 and ARPC4 in the invasion of cells by gram-negative bacteria have been widely reported, for example, both are involved in the pathogenic E. coli, Salmonella, and Yersinia infection pathways." (PMID 36090174, 2022).
cancer (5 papers, 2021 to 2025). A tumor composed of atypical neoplastic, often pleomorphic cells that invade other tissues. "We further tested the function of ARPC4 in primary T cells using an in vitro cancer cell-killing assay." (PMID 38073578, 2024). "Genes differing insignificantly from healthy tissue were IMP-3, CDH1, IQGAP1, NEDD9, TKS5, WAS and ARPC4, indicating minimal alterations in their expression levels in the analyzed cancer samples." (PMID 37623256, 2023).
tumor (3 papers, 2017 to 2024). "Regarding pathway assignments of at least 20 HRO tumours, 10 top-ranked genes, of which 9 were lost in 3p, were linked with 7 to 45 pathways (n = 280) comprising RAF1 (45 PWs), RHOA (25 PWs), IPTR1 (22 PWs), CACNA1D, ITGA9 (8PWs), WNT7A (8 PWs) TLR9 (7PWS9, LAMB2 (7 PWs) and ARPC4 (6 PWs)." (PMID 28486536, 2017). "Through large-scale CRISPRi screening, we discovered genetic modifiers in GBM cells, including ARPC4, PI4KA, ATP6V1A, UBA1, and NDUFV1, that regulated the efficacy of CAR T cell-mediated tumor killing." (PMID 38561797, 2024).
infection (2 papers, 2011 to 2021). The state of being infected such as from the introduction of a foreign agent such as serum, vaccine, antigenic substance or organism. "As expected, in ARPC4-depleted cells, infection with wild-type bacteria displayed a spreading defect phenotype similar to the one observed in wild-type cells infected with the ΔactA mutant strain (ARPC4, 10403S)." (PMID 21853127, 2011). "Then, we investigated the expression of Arpc4 and Arpc5 during infection with V. splendidus." (PMID 34898657, 2021).
ARPC4 also shares sentences with these, for which no sentence is quoted: lung carcinoma (2 papers); Alzheimer disease (1); atherosclerosis (1); bladder cancer (1); breast carcinoma (1); gastric carcinoma (1); genetic disorders (1); glioblastoma (1); microcephaly (1); Thrombocytopenia (1).